LIF (LIF interleukin 6 family cytokine)
Diseases named in the same sentence as LIF in open-access papers (continued):
Sharing a sentence is not in itself a finding about the gene and the disease.
Infertility (continued). "Other studies reported that endometrial LIF and receptor were higher around the time of implantation in fertile women compared with women with unexplained infertility." (PMID 35251378, 2022). "The expression of integrins has also been reported to be diminished in the endometrium of infertile patients and affected by LIF." (PMID 33809755, 2021). "It has been revealed that compared to fertile women, women with unexplained infertility have high endometrial levels of the inhibitor of LIF, SOCS1, accompanied by low levels of LIF receptor (LIFR) and gp130." (PMID 34496883, 2021). "Mechanistically, the infertility in these mice is attributed to low expression of leukemia inhibitory factor (LIF), and Indian hedgehog (IHH)." (PMID 32244282, 2020). "In fertile women, LIF expression increases in the endometrium around the time of implantation, while infertile women express low levels of this factor." (PMID 31861484, 2019). "Intraperitoneal injection of peritoneal fluid collected from infertile women with endometriosis decreased the implantation rate in a rodent model, as well as endometrial integrin αvβ3 and LIF expression." (PMID 30104541, 2018). "LIF mRNA is expressed in the endometrium of normal fertile women but is significantly decreased in infertile women." (PMID 28830391, 2017). "The role of the LIF gene allele and the hormonal stimulation were hypothesized, the aim of the study was to determine whether a diagnosed cause of infertility is directly related to 3400 G>A LIF gene mutation, reflected in women with various causes of infertility." (PMID 28845418, 2017). "Previous studies have reported a lower expression of GdA, progesterone receptor B and LIF in the mid-secretory endometrium of infertile women." (PMID 25981399, 2015). "Further assessment of uterine luminal fluid indicated that endometrium of infertile women secretes significantly lesser amount of LIF and gp130 than normal fertile women between luteal days (LH) 6 to 13 which coincides with implantation window period." (PMID 25152902, 2014). "Meanwhile, mice with gp130 mutation and STAT-binding site deletion are also infertile indicating that gp130 and STAT are essential in regulating LIF action." (PMID 25152902, 2014). "A moderate to high LIF expression was detected during the proliferative and secretory phases of the menstrual cycle in normal fertile women with low expression observed in infertile women with implantation failure." (PMID 25152902, 2014). "Endometrial aspirations from infertile women contain less LIF than those obtained from fertile patients." (PMID 23508459, 2012). "Expression of LIF in endometrium was significantly lower in infertile women compared with fertile women (P < 0.001)." (PMID 22520363, 2012). "Based on these finding, this study was designed to investigate the expression of LIF and its receptor subunit gp130 in endometrium of infertile women." (PMID 22520363, 2012). "In consequence, the ratio of LIF/sgp130 and IL-6/sgp130 is altered in endometrium of infertile women." (PMID 22520363, 2012). "In particular, it has been demonstrated that the so-called Leukemia Inhibitory Factor (LIF) is associated with endometrial receptivity and is lower in women with infertility compared with healthy controls." (PMID 22242025, 2012). "Secretion of LIF in uterine flushing samples was significantly lower in infertile women than in fertile women (P < 0.001)." (PMID 22520363, 2012). "LIF mRNA was expressed in the endometrium of all normal fertile women but significantly decreased in infertile women." (PMID 22520363, 2012). "So too in humans LIF appears to be involved in egg implantation, given that LIF levels are significantly decreased in women with unexplained infertility." (PMID 22532853, 2012). "We started our study by confirming the expression of LIF mRNA in the endometrium of both fertile and infertile women during the implantation window." (PMID 22520363, 2012).
Infertility (continued). "Expression of LIF mRNA in the endometrium was significantly reduced in infertile women compared with the fertile group." (PMID 22520363, 2012). "The present study shows that secretion of LIF in samples of uterine flushing of infertile women during window of implantation was markedly low." (PMID 22520363, 2012). "The LIF−/− mouse is infertile due to failure of implantation and shows decreased bone volume associated with increased osteoclast number and size." (PMID 21611124, 2011). "Evidence for an important role of LIF in human implantation comes from clinical studies of infertile women, who have lower levels of LIF mRNA and protein in endometrial tissue and LIF protein in uterine flushings than fertile women." (PMID 21611124, 2011). "Endometrial protein abundance for IL-11, pSTAT3, IL-11Rα and LIF was compared in women with primary unexplained infertility and normal fertile women." (PMID 18047677, 2007). "Immunoreactive LIF is reduced in endometrial biopsies from infertile women, while uterine flushings contain maximum levels of LIF protein during the mid to late secretory phase of the menstrual cycle." (PMID 18047677, 2007). "For example, in some women with infertility and repetitive miscarriage, low levels of LIF in MSE have been reported, as have point mutations in the coding region of the LIF gene." (PMID 17118168, 2006). "CE can lead to a decrease in the level of LIF, thus causing abnormalities in the JAK2‐STAT3 signaling pathway, affecting endometrial receptivity, and ultimately leading to embryo implantation failure, which is a possible pathogenesis of CE infertility." (PMID 38896093, 2024). "Accordingly, impairments in endometrial LIF expression may significantly contribute to pathological processes involving implantation and infertility." (PMID 38297297, 2024). "Alterations to Leukemia Inhibitory Factor (LIF), a cytokine produced by the luminal and glandular epithelium of the endometrium that is imperative for successful pregnancy, have been postulated to contribute to infertility." (PMID 37033980, 2023). "The FOXA2-deficient mouse was infertile due to defects in embryo attachment and a lack of LIF expression on day 4 of pregnancy." (PMID 37108290, 2023). "Conditions such as recurrent implantation failure, unexplained infertility, and infertility associated diseases such as adenomyosis and endometriosis, have demonstrated reduced LIF production in the endometrium of infertile patients compared to fertile counterparts." (PMID 37033980, 2023). "Our study also revealed a significantly higher rate of the TG/GG genotype and the G allele of LIF (rs929271) in younger patients with infertility (group 1 and 3) but not in older patients (group 2 and 4) among the patients with poor response." (PMID 36769444, 2023). "One study demonstrated that GT/GG genotypes and the G allele of LIF (rs929271) are significantly enriched in patients with infertility under the age of 35 years, but not in older patients with unexplained infertility." (PMID 36769444, 2023). "Consistently it has been shown through immunohistochemistry (IHC) of the endometrium that the infertile cohorts- regardless of cause, have reduced endometrial LIF protein expression compared to fertile controls." (PMID 37033980, 2023). "Previous investigations of LIF in relation to implantation have been focused mainly on the population study of infertile women versus fertile women, while the measurement of LIF in endometrial cavity during peri-implantation of a fresh IVF cycle has yet been studied." (PMID 35224652, 2022). "Defects in endometrial LIF expression have been reported in many infertile patient groups." (PMID 35012573, 2022). "Importantly, LIF expression has been found to be lower in women suffering from endometriosis, suggesting that LIF expression is a vital marker of infertility in women with endometriosis." (PMID 35273494, 2022).
Infertility (continued). "Moreover, a dysregulation of LIF production in the endometrium was observed in the great majority of infertile women during both the proliferative and secretory phases of the menstrual cycle." (PMID 35216313, 2022). "LIF null female mice are infertile due to implantation failure." (PMID 34558134, 2021). "LIF gene mutation does not frequently occur in infertile women, and recombinant human LIF did not improve implantation rates after in vitro fertilization (IVF)." (PMID 33809755, 2021). "It is likely that the function of SOCS1 and LIF are affected in these women with infertility, and these disturbances in the SOCS1 pathway could possibly explain the infertility of women with RIF." (PMID 34496883, 2021). "Ganesh and co-workers found that when patients with unexplained infertility were treated with letrozole or CC, endometrial receptivity markers such as αvβ3 integrin, L-selectin, leukemia inhibitory factor (LIF), and pinopod concentrations were meaningfully higher compared to controls." (PMID 32309769, 2020). "Endometrial expression of LIF and VEGFA is altered in diabetic rats during implantation which may be associated with diabetic-related infertility." (PMID 33062917, 2020). "The expressions of LIF and VEGFA were altered in diabetic rats during implantation which may be associated with diabetic-related infertility." (PMID 33062917, 2020). "LIF-knockout female mice are infertile due to embryo implantation failure." (PMID 32023940, 2020). "LIF and its receptor have been shown to be reduced in the endometrium of infertile women." (PMID 30061528, 2018). "Furthermore, several studies have suggested that LIF and LIF receptor expressions are significantly low in the endometrium of infertile women." (PMID 30061528, 2018). "From April 2015 to October 2015, we screened 60 non-selected infertile women and 80 fertile controls with at least one live birth for LIF gene mutations in Tabriz University of Medical Science, Tabriz, Iran." (PMID 28845418, 2017). "In uterine flushing samples, LIF was undetectable in 88% of infertile women." (PMID 28830391, 2017). "We postulated that for infertile women achieving pregnancy, LIF would likely be up-regulated." (PMID 28830391, 2017). "LIF gene mutation in infertile women was significantly increased and had a negative impact on the in vitro fertilization (IVF) outcome." (PMID 29085337, 2017). "STAT3 signaling involving the leukemia inhibitory factor (LIF) is critical for embryo implantation and reproductive fertility, and LIF deficiency is associated with unexplained recurrent abortion and infertility in women and inactivation of STAT3 causes pregnancy failure." (PMID 26681200, 2015). "It has also been shown that LIF expression is decreased in the endometrium in women with adenomyosis during midsecretory phase and, when these women have a history of infertility, they show significantly lower LIF levels in uterine flushing fluid, compared with fertile controls." (PMID 22242025, 2012). "Several studies have reported lower LIF in uterine flushing samples from women with primary unexplained infertility than in fertile women, and lower LIF secretion from endometrial explants of infertile women than fertile ones, especially during the implantation window." (PMID 22520363, 2012). "Expression of LIF mRNA in endometrium could be used as a molecular marker of unexplained infertility." (PMID 22520363, 2012). "In infertile women, uterine flushing LIF levels varied between 0.5 and 35 pg/ml (mean: 3.9 ± 7.5)." (PMID 22520363, 2012).
Infertility (continued). "In addition, LIF expression in the endometrium in the secretory phase was 22-fold higher than that of the proliferative phase in females with a history of pregnancy, but LIF expression in the secretory phase is dramatically reduced in females with infertility." (PMID 23226768, 2012). "LIF null female mice are infertile due to the failure of blastocysts to implant into the uterus." (PMID 21611124, 2011). "LIF mRNA and protein is maximally expressed in the murine endometrial glandular epithelium just prior to blastocyst implantation: LIF−/− female mice are infertile due to implantation failure: blastocysts cannot adhere to the endometrial luminal epithelium." (PMID 21966484, 2011). "It is also plausible that IL-11 and LIF stimulate pSTAT3 in glandular epithelium but the levels of STAT3 protein may be low in glandular epithelium of some infertile women." (PMID 18047677, 2007). "While LIF was not significantly reduced in the endometrial glands of women with infertility, LIF action could be impaired in women with low glandular pSTAT3." (PMID 18047677, 2007). "We hypothesized that IL-11, IL-11Rα, LIF and pSTAT3 are dysregulated in endometrium from women with unexplained infertility during the 'window of implantation'." (PMID 18047677, 2007). "Several previous reports have demonstrated that CE decreases the level of LIF, thus causing the abnormal function of the JAK2/STAT3 signaling pathway, which affects endometrial receptivity and ultimately leads to embryo implantation failure and is a possible pathogenesis of CE infertility." (PMID 38896093, 2024). "While it is known that some endometriosis patients experience alterations to eutopic LIF production, it is still not known whether this is a consequence of endometriosis associated infertility or whether this contributes to endometriosis pathophysiology." (PMID 37033980, 2023). "Thus, continued investigation is needed to determine whether LIF dysregulation is specific to endometriosis patients with infertility or whether it can be found in fertile patients as well." (PMID 37033980, 2023). "Notably, the loss of LIF in this model was not the only cause of the infertility as administration of recombinant LIF did not rescue the implantation phenotype." (PMID 30356064, 2018). "Moreover, LIF expression waslower in patients with endometriosis and infertility(p<0.05)." (PMID 28967712, 2017). "Indeed, we found that LIF was 12.25-fold higher among infertile women who achieved pregnancy, suggesting that augmenting LIF expression could promote implantation and pregnancy." (PMID 28830391, 2017). "Likewise, endometrial explants derived from infertile women showed reduced levels of LIF secretion." (PMID 22520363, 2012). "In conclusion, the study indicates the possibility that endometrium of women with idiopathic infertility has abnormalities in expression and secretion of important cytokines as LIF and its gp130 receptor molecules, which may contribute to altered uterine receptivity and so infertility." (PMID 22520363, 2012). "Second, we compared the distribution of LIF (rs929271) and FSHR (rs6166) in patients with infertility with an adequate ovarian reserve (POSEIDON group 1 and 2) with normal responders." (PMID 36769444, 2023). "LIF (rs929271) and FSHR (rs6166) should be considered as potential biomarkers for poor or suboptimal COH responses among young and older women with infertility who are expected to be normal responders." (PMID 36769444, 2023). "Among altered cytokines, leukemia inhibitory factor (LIF), a member of IL-6-like family E2-responsive, essential for blastocyst implantation, also shows reduced expression in infertile patients with endometriosis, especially at moderate stages of the disease." (PMID 32063886, 2019). "The results reveal a reduction in LIF, its receptor LIFR, and the signal transducing chain gp130 in patients with unexplained infertility, endometriosis, and recurrent implantation failure." (PMID 27239344, 2016).
Infertility (continued). "We conducted a comprehensive review (PubMed search up to April 2025) using keywords related to the Warburg effect (aerobic glycolysis, lactate, mitophagy), infertility (IVF, embryo implantation, TCM), cancer, cytokines (IL-1, LIF, TGF-β), and hormones (estrogen, progesterone)." (PMID 41332984, 2025). "Serum LIF in first trimester was significantly lower in women who were conceived after ART and later developed preeclampsia in previous research using bioinformatics and expressed lower in infertile endometrium." (PMID 41006365, 2025). "LIF expression is generally higher during the WOI in fertile women as opposed to patients experiencing infertility." (PMID 39274229, 2024). "Importantly, in infertile women, the levels of LIF, LIFR, and gp130 in the endometrium were significantly reduced, suggesting that LIF and its receptors influence female pregnancy." (PMID 39062484, 2024). "With regard to the clinical implications of our findings, LIF (rs929271) and FSHR (rs6166) analysis should be considered for young and older women with infertility who are expected to be normal responders but who exhibit an unexpectedly poor or suboptimal COH response." (PMID 36769444, 2023). "The lack of uterine glands or LIF-null animals including mice and sheep exhibits the infertile phenotype indicating that gland-derived substances are necessary for the development and maintenance of pregnancy." (PMID 37108290, 2023). "Thereafter, we could consider genotyping LIF (rs929271) and FSHR (rs6166) among young and older women with infertility who are expected to be normal responders before they enter their first ART to avoid an unexpected or a hypo-response." (PMID 36769444, 2023). "Studies showing the role of LIF signaling in infertility have generated interest in targeting this cytokine as a potential non-hormonal birth control, or increasing LIF as a treatment to improve IVF outcomes." (PMID 35204717, 2022). "Using a relatively small cohort of hyperstimulated women with diverse etiologies of infertility, administration of LIF did not improve pregnancy outcomes." (PMID 32244282, 2020). "Only 3 (12%) of the 25 infertile women enrolled in the study showed detectable endometrial LIF expression; 22 patients (88%) did not showed any LIF mRNA in their endometrial samples." (PMID 22520363, 2012). "IL-11, pSTAT3, IL-11Rα and LIF staining was overall low and patchy or absent in luminal epithelium of both infertile and fertile women." (PMID 18047677, 2007). "In a previous study, while LIF production was not different between women with unexplained infertility and normal fertile women, there was reduced secretion of soluble gp130 from endometrial explants." (PMID 18047677, 2007). "These inflammatory mediators were hypothesized to be a contributor to patient infertility yet the broader implications of LIF dysregulation within endometriosis pathophysiology have not been speculated upon and remain to be explored." (PMID 37033980, 2023). "Women with infertility under 35 years who have TG or GG phenotypes of LIF (rs929271) may exhibit unexpectedly poor or suboptimal responses during COH, and LIF may affect folliculogenesis both in gonadotropin-independent growth and gonadotropin-dependent growth." (PMID 36769444, 2023). "Furthermore, in infertile women with RIF, the LIF level fell in the secretory phase." (PMID 38139443, 2023). "LIF was not detectable in 88% of infertile women while it was fairly detectable in 12% of them." (PMID 22520363, 2012).